TRAV34 (T cell receptor alpha variable 34)
Description:
V region of the variable domain of T cell receptor (TR) alpha chain that participates in the antigen recognition. Alpha-beta T cell receptors are antigen specific receptors which are essential to the immune response and are present on the cell surface of T lymphocytes. Recognize peptide-major histocompatibility (MH) (pMH) complexes that are displayed by antigen presenting cells (APC), a prerequisite for efficient T cell adaptive immunity against pathogens. Binding of alpha-beta TR to pMH complex initiates TR-CD3 clustering on the cell surface and intracellular activation of LCK that phosphorylates the ITAM motifs of CD3G, CD3D, CD3E and CD247 enabling the recruitment of ZAP70. In turn ZAP70 phosphorylates LAT, which recruits numerous signaling molecules to form the LAT signalosome. The LAT signalosome propagates signal branching to three major signaling pathways, the calcium, the mitogen-activated protein kinase (MAPK) kinase and the nuclear factor NF-kappa-B (NF-kB) pathways, leading to the mobilization of transcription factors that are critical for gene expression and essential for T cell growth and differentiation. The T cell repertoire is generated in the thymus, by V-(D)-J rearrangement. This repertoire is then shaped by intrathymic selection events to generate a peripheral T cell pool of self-MH restricted, non-autoaggressive T cells. Post-thymic interaction of alpha-beta TR with the pMH complexes shapes TR structural and functional avidity.
Synonyms: TCRAV26S1; TCRAV34S1
Gene: T-cell receptor variable (V) gene on chromosome 14 (22,207,522 to 22,208,129, forward strand). Ensembl gene ENSG00000211813.
Subcellular location: Cell membrane
Gene Ontology:
Biological process: response to bacterium
Cellular component: plasma membrane
Homologues: Orthologues: macaque TRAV34 (79% identical), dog TRAV34 (60% identical), mouse Trdv1 (59% identical). Paralogues in human: TRAV30 (57% identical), TRAV27 (46% identical), TRAV10 (40% identical), TRAV17 (39% identical), TRAV25 (39% identical), TRAV21 (38% identical), TRAV20 (38% identical), TRAV39 (38% identical), TRAV6 (38% identical), TRAV24 (37% identical), TRAV36DV7 (36% identical), TRAV5 (33% identical), and 11 more.
Diseases named in the same sentence as TRAV34 in open-access papers:
TRAV34 is named in the same sentence as 1 disease in open-access papers, as found by Europe PMC text mining. Sharing a sentence is not in itself a finding about the gene and the disease. The quoted sentences say what the papers report.
carcinoma (1 paper, 2021). A malignant tumor arising from epithelial cells. "However, the functions of TRAV34, GTSF1L, LILRA4, and GNG8 in carcinoma remain unclear." (PMID 34844217, 2021).